IRF8 (interferon regulatory factor 8)
Diseases named in the same sentence as IRF8 in open-access papers (continued):
Sharing a sentence is not in itself a finding about the gene and the disease.
osteoporosis (8 papers, 2014 to 2023). A condition of reduced bone mass, with decreased cortical thickness and a decrease in the number and size of the trabeculae of cancellous bone (but normal chemical composition), resulting in increased fracture incidence. "Consistent with this, mice deficient in IRF8 showed severe osteoporosis due to increased OC formation, and enhanced bone destruction following LPS administration." (PMID 35011694, 2021). "Further, IRF8-deficient mice showed osteoporosis accompanied by an increased number of osteoclasts." (PMID 34571873, 2021). "Thus, if most osteoclasts differentiate from BMMs in vivo, then Irf8fl/fl;Lyz2cre/+ mice should develop osteoporosis caused by enhancement of excessive bone resorption induced by osteoclastogenesis, the same as seen in Irf8−/− mice." (PMID 27502007, 2017). "IRF8 inhibits osteoclastogenesis, and is involved in the development and progression of osteoporosis." (PMID 37600656, 2023). "The expression of IRF8 in OC precursors is downregulated during the initial phase of RANKL-induced OC differentiation, and IRF8-deficient mice exhibit severe osteoporosis owing to the increased number of OCs." (PMID 36362318, 2022). "Nevertheless, elevation or stabilization of these inhibitory proteins, including TRAF3, p100, IRF8, and RBP-J, would be a novel strategy to treat a variety of bone diseases with bone loss, including osteoporosis and RA." (PMID 35011694, 2021). "Although genome-wide association studies have identified positive genetic associations with markers in the proximity of the IRF1 (5q31.1) and IRF8 (16q24.1) genes, a role for these genes and their targets in clinical osteoporosis needs to be formally tested." (PMID 24954358, 2014). "Likewise, it will be interesting to investigate a possible role of IRF1 and of its heterodimerization partner IRF8 in human disorders characterized by osteopenia, such as osteoporosis." (PMID 24954358, 2014). "Irf8 mRNA expression was not reduced in BMCs from Irf8fl/fl;Lyz2cre/+ mice and those mice did not demonstrate osteoporosis." (PMID 27502007, 2017). "In contrast to Irf8−/− mice, the Irf8fl/fl;Lyz2cre/+ mice did not develop osteoporosis." (PMID 27502007, 2017).
glioma (7 papers, 2016 to 2022). A benign or malignant brain and spinal cord tumor that arises from glial cells (astrocytes, oligodendrocytes, ependymal cells). "For instance, IFNγ stabilises Irf8 activation in glioma cells and microglial C5/C5a complement component induced TMZ resistance." (PMID 36555253, 2022). "The combined model encompassing JAK-STAT and IRF8 offered an additional resolution in patient stratification: glioma (full-cohort, P < 0.0001), astrocytoma (P = 0.0007), pan-kidney (P < 0.0001) and clear cell renal cell (P < 0.0001)." (PMID 31684858, 2019). "In summary, this study showed that IRF1, IRF2, IRF5, IRF8, and IRF9 mRNA levels were increased in glioma compared to normal tissue." (PMID 33902005, 2021). "We found that IRF1, IRF2, IRF5, IRF7, IRF8, and IRF9 were upregulated in glioma compared with normal tissue." (PMID 33902005, 2021). "We found that IRF1, IRF2, IRF5, IRF8 and IRF9 were significantly upregulated in glioma compared to normal brain tissue." (PMID 33902005, 2021). "Overall survival curves indicated that glioma patients with lower IRF1 (p = 4.42E-33), IRF2 (p = 2.22E-16), IRF3 (p = 1.43E-15), IRF4 (p = 0.004), IRF5 p = 5.84E-12), IRF7 (p = 6.85E-28), IRF8 (p = 0.001), and IRF9 (p = 0.000) transcript levels had significantly longer overall survival times." (PMID 33902005, 2021). "Collectively, these results indicate that IRF family members, including IRF1, IRF2, IRF5, IRF8 and IRF9, may serve as prognostic biomarkers and indicators of immune status in glioma patients." (PMID 33902005, 2021). "By analyzing the glioma data in the TCGA database, the expression level of SPI1 displayed a significant positive correlation with target genes (CX3CR1: r = 0.53; CSF1R: r = 0.876; IRF8: r = 0.678)." (PMID 34434898, 2021). "Likewise, IRF8, a transcription factor for the function and development of microglia cells is expressed simultaneous with P2RY12 in both GBM and low grade gliomas." (PMID 28073370, 2017). "Among the 260 grade II, 267 grade III, and 173 grade IV glioma patients, significant correlations were observed between IRF1 (p = 8.00E-61), IRF2 (p = 6.80E-18), IRF3 (p = 1.70E-23), IRF5 (p = 2.30E-08), IRF7 (p = 1.90E-29), IRF8 (p = 0.029), IRF9 (p = 4.80E-05) expression and pathological grade." (PMID 33902005, 2021).
inflammatory bowel disease (7 papers, 2013 to 2024). A spectrum of small and large bowel inflammatory diseases of unknown etiology. "We thank Dr. Michel Georges (University of Liège, Belgium) for insightful comments on the association of IRF8 alleles in inflammatory bowel diseases, and for critical reading of this manuscript." (PMID 23853600, 2013). "IRF8 plays various and important regulatory roles in the growth, differentiation, and function of immune cells in inflammatory bowel disease (IBD) patients." (PMID 32766317, 2020).
tuberculosis (7 papers, 2011 to 2022). A chronic, recurrent infection caused by the bacterium Mycobacterium tuberculosis. "A Chinese study identified three SNPs in the IRF8 gene (rs925994, rs11117415, and rs10514611) to be associated with susceptibility to tuberculosis." (PMID 31178872, 2019). "Parallel analysis of lungs infected with Mycobacterium tuberculosis show that IRF8-associated core pathways are also engaged during tuberculosis where they play a protective role." (PMID 23853600, 2013). "Genes encoding IRF1 and IRF8 protein have been proposed as candidate tuberculosis susceptibility genes." (PMID 22879909, 2012). "In order to elucidate whether the IRF1 and IRF8 variants were associated with tuberculosis susceptibility, we conducted a case-control study consisting of 495 controls and 452 ethnically matched cases with tuberculosis in a Chinese population." (PMID 22879909, 2012). "Our results indicated that the IRF8 gene might participate in genetic susceptibility to tuberculosis in a Chinese population." (PMID 22879909, 2012). "IRF-8 polymorphisms have been implicated in the development of autoimmune thyroiditis, Behcet’s disease and, increased susceptibility to tuberculosis (TB)." (PMID 36078039, 2022). "Chromatin immunoprecipitation and RNA sequencing studies of genes bound and activated by IRF8, IRF1, PU.1, and STAT1, revealed the existence of an IRF1/IRF8 regulome, which plays critical roles in inflammatory and antimicrobial defense, such as neuroinflammation and tuberculosis." (PMID 31178872, 2019). "In the IRF8 gene, interestingly, we found that three tagSNPs (rs925994 and rs11117415 located in the intron region; rs10514611 located in the 3′UTR) were associated with risk of tuberculosis after Bonferroni correction." (PMID 22879909, 2012). "Irf8-deficient mice, then, display defective Th1 responses (absence of antigen specific and IFNγ producing CD4+ T cells), enhanced Th17 responses, and are susceptible to in vivo infection with many intracellular pathogens including tuberculosis and blood-stage malaria." (PMID 23853600, 2013).
COVID-19 (6 papers, 2021 to 2023). A disease caused by infection with severe acute respiratory syndrome coronavirus 2. "IRF8, which was shown to be significantly reduced in COVID-19, promotes macrophage and dendritic cell differentiation and has a critical role in autophagy, antigen presentation, and clearing intracellular pathogens." (PMID 36672197, 2023). "In line with this, we found that mRNA levels of IRF8 in mild and severe COVID-19 patients were significantly reduced compared to healthy donors." (PMID 33692788, 2021). "Ultimately, EEF1A1, EGR1, UBA52, DDX5 and IRF8 might be the key shared pathogenesis-related genes in COVID-19 and asthma." (PMID 36575422, 2022). "We prioritized 4 out of 5 microglia PFC TFs (IRF8, ATF5, SPI1, TAL1) based on the upregulation in their activity in patients with COVID-19 (Z > 2.5, P < 0.05 and FDR within cell type < 0.05)." (PMID 34281603, 2021). "Overall, down-regulated IRF-8 and autophagy-related genes expression, and the expansion of MDSC subsets could play critical roles in dysregulating T cell response in COVID-19, which could have large implications in diagnostics and design of novel therapeutics for this disease." (PMID 33692788, 2021). "However, additional investigations are necessary to clarify the roles of IRF-8 expression in specific subsets of PBMC, which could be beneficial for developing novel therapeutic approaches modulating IRF8-dependent pathways in COVID-19." (PMID 33692788, 2021).
hepatocellular carcinoma (6 papers, 2015 to 2025). A malignant tumor that arises from hepatocytes. "A low level of IRF8 expression in tumors is associated with poor prognosis in human hepatocellular carcinoma (HCC), and gene set enrichment analysis identified the IFNγ and PD-1 signaling signatures as the top suppressed pathways in patients with IRF8-low HCC." (PMID 36672246, 2023). "Continued investigation on anti-PD-L1 therapy has shown that, in hepatocellular carcinoma, IRF8 enhances the response to treatment and suppressed progression." (PMID 36078039, 2022).
lymphoma (6 papers, 2011 to 2025). A malignant (clonal) proliferation of B- lymphocytes or T- lymphocytes which involves the lymph nodes, bone marrow and/or extranodal sites. "Fortuitously, we detect a significant impact of IRF8 KO or mutation in an assay (CD4 DO-11.10 cells activation) in which the antigen loaded into the lymphoma cells was already processed (the OVA peptide)." (PMID 38996030, 2024). "Mice harboring IRF8-mutant lymphomas displayed larger tumor burden, in association with remodeling of the TME, an immunophenotype that was rescued in vivo by ectopic expression of CD74 and validated in primary human DLBCLs." (PMID 38996030, 2024). "This cohort of 480 DLBCLs was first reanalyzed for IRF8 mutation calling, and a total of 45 lymphomas were found to harbor an IRF8 variant allele." (PMID 38996030, 2024). "We concluded that missense and truncating IRF8 mutation rewires the lymphoma microenvironment toward a broad procancer profile." (PMID 38996030, 2024). "All mice with deficiencies of IRF-4 and IRF-8 finally developed B lymphoblastic leukemia/lymphoma at the age of 25 weeks, and then died." (PMID 35211408, 2022). "IRF8 mutations contribute to lymphoma pathogenesis by promoting immune escape." (PMID 38996030, 2024). "Using exome sequencing, they identified six recurrent, rare, and potentially deleterious variants within 5 kb of lymphoma-associated GWAS loci in 75 MM cases (BTNL2, EOMES, TNFRSF13B, IRF8, ACOXL, TSPAN32)." (PMID 41300981, 2025). "Mice harboring lymphomas expressing IRF8 N87Y, Q392X, and I424T displayed significantly increased tumor growth." (PMID 38996030, 2024). "To test this possibility, we designed a treatment trial in which, following tumor engraftment, mice harboring IRF8-WT or IRF8-N87Y lymphomas were dosed with an anti–PD-L1 antibody or control antibody every 72 hours." (PMID 38996030, 2024). "Mice harboring IRF8 mutant lymphomas displayed higher tumor burden and remodeling of the tumor microenvironment, typified by depletion of CD4, CD8, and natural killer cells, increase in regulatory T cells and T follicular helper cells." (PMID 38996030, 2024). "In mice, the IRF8-mutant driven remodeling of the lymphoma microenvironment was diverse but consistently reflected a procancer profile (decrease in CD4, CD8, NK, and TFH1 and increase in Tregs and TFH cells)." (PMID 38996030, 2024). "This perturbation increases tumor aggressiveness of IRF8-mutant lymphomas, which is clinically and immunologically corrected by CD74 expression or anti–PD-L1 treatment." (PMID 38996030, 2024). "Additional studies showed that among mouse and human B lineage cells IRF8 is expressed at the highest levels in germinal center (GC) B cells and lymphomas of GC origin but is extinguished in terminally differentiated plasma cells and plasma cell neoplasms." (PMID 22096565, 2011). "The T cell depletion in the TME of IRF8-mutant lymphomas was confirmed using IHC." (PMID 38996030, 2024). "Together, these data confirm that the role of IRF8 mutations is recognized principally in vivo, furthering the concept that immune escape, rather than a lymphoma cell intrinsic effect, is at the core of IRF8 dysfunction in B cell lymphomas." (PMID 38996030, 2024). "To test whether the IRF8 mutant–driven remodeling of the lymphoma microenvironment found in mouse models of B cell lymphoma could be recapitulated in primary human DLBCL, we used deconvolution of bulk RNA sequencing (RNA-seq) data (dbGaP Study Accession: phs001444.v2.p1)." (PMID 38996030, 2024). "The potential link between IRF8 and Tregs emerged more recently, when IRF8 mutations in relapsed DLBCL was identified as a putative marker for poor response to CD19-CAR T cells, possibly in association with an increase in Tregs in the lymphoma microenvironment." (PMID 38996030, 2024).
lymphoma (continued). "This reduced tumor aggressiveness was accompanied, and possibly secondary to, a marked remodeling of the TME, which after CD74 ectopic expression was not significantly different between IRF8 WT and IRF8 mutant lymphomas." (PMID 38996030, 2024). "We concluded that in the DLBCL models tested, IRF8 mutations did not stimulate cell growth and were more akin to KO models, which led us to consider the possibility that these variants may represent a cancer cell intrinsic defect that primarily influences the lymphoma microenvironment." (PMID 38996030, 2024). "Early on, it was shown that IRF8 is constitutively expressed by normal mouse B cells and lymphoma cell lines with features of pro-B and pre-B cells but not by plasmacytomas, tumors of mature plasma cells." (PMID 22096565, 2011).
myeloma (6 papers, 2016 to 2024). "Real time PCR analysis and western blot revealed that monocytes NFATc1 mRNA and proteins levels are higher, IRF8 protein levels are lower treated with myeloma cells exosomes as compared to untreated cells or healthy plasma cell exosomes treated cells." (PMID 36451863, 2022). "These experiments demonstrate that myeloma cells hnRNPA2B1 regulated monocytes IRF8 and NFATc1 or MSCs RUNX2 expression through exosomes miR-92a-2-5p or miR-373-3p." (PMID 36451863, 2022). "TFs like KLF4 and IRF8 were up-regulated in osteocytes co-cultured with myeloma cells in comparison with osteocytes cultured alone." (PMID 27405725, 2016). "Finally, osteolytic changes in myeloma patients have been reported to be related to an increase in IRF8 methylation and IRF8 down-expression." (PMID 35163424, 2022). "In conclusion, a total of 393 DEGs were identified between osteocytes co-cultured with and without myeloma cells, and KLF4, IRF8, EGF, EGR1, S1PR1, C3AR1, and NPY1R might be involved in osteocyte cell apoptosis induced by MM cells." (PMID 27405725, 2016). "We do not believe that the observed effects might be explained by DAC induced toxicity since a previous study showed that treating human multiple myeloma cell lines with the same 10 μM DAC as used in our study, could restore the mRNA expression of IRF8 without showing toxicity." (PMID 28432342, 2017).
Alzheimer disease (5 papers, 2016 to 2023). A progressive, neurodegenerative disease characterized by loss of function and death of nerve cells in several areas of the brain leading to loss of cognitive function such as memory and language. "Recent evidence indicates that IRF8 affects behavior and modulates Alzheimer’s disease progression in a mouse model." (PMID 38239832, 2023).
cardiac hypertrophy (5 papers, 2015 to 2024). "Moreover, the cardiac-specific overexpression of IRF8 in mice was found to be protective against aortic banding-induced cardiac hypertrophy." (PMID 31850068, 2019).
diabetes (5 papers, 2011 to 2023). "IRF8, another candidate gene important in regulating Th2 immune response, has been suggested to play an important role in diabetes development." (PMID 21647406, 2011). "In the present study, we have investigated the expression of IRF4 and IRF8 genes in splenocytes and DCs of diabetes-prone NOD mice and compared the results to diabetes-resistant NOR and BALB/c mice." (PMID 21647406, 2011). "However, the role of IRF8 in DN, which is also a microvascular complication of diabetes, still needs to be further investigated." (PMID 37250717, 2023). "Together, these results suggested that gene and protein expression levels of IRF4 were upregulated in the spleen of diabetes-prone NOD mice whereas levels of IRF8 remained unchanged at 3 and 7 weeks of age, and were slightly increased in 10 and 20 weeks old mice when compared to BALB/c mice." (PMID 21647406, 2011). "In contrast, the increased IRF8 expression in the spleen of diabetes-prone NOD mice may be the result of a high production of IFNγ which is known to induce IRF8 expression in macrophages and T cells." (PMID 21647406, 2011). "Further investigation on the role of IRF4 and IRF8 in diabetes development may help to determine whether IRF4 and/or IRF8 could be potential targets for therapeutic interventions in type 1 diabetes." (PMID 21647406, 2011). "The results of the interactions show that LAPTM5, IRF8, IGTB2, CD53, and C1QB scored higher with diabetes mellitus." (PMID 37113991, 2023). "In contrast, IRF8 expression remained unchanged in splenic DCs of NOD and diabetes-resistant BALB/c mice although it was significantly increased in immunogenic BMDCs but not in tolerogenic BMDCs of NOD mice." (PMID 21647406, 2011). "In a first series of experiments, we used quantitative PCR (qPCR) to assess gene expression of IRF4 and IRF8 in splenocytes isolated from prediabetic and diabetic NOD mice as well as control diabetes-resistant congenic NOR and BALB/c mice." (PMID 21647406, 2011).